ARHGEF7 (Rho guanine nucleotide exchange factor 7)
Description:
Acts as a RAC1 guanine nucleotide exchange factor (GEF) and can induce membrane ruffling. Functions in cell migration, attachment and cell spreading. Promotes targeting of RAC1 to focal adhesions (By similarity). May function as a positive regulator of apoptosis. Downstream of NMDA receptors and CaMKK-CaMK1 signaling cascade, promotes the formation of spines and synapses in hippocampal neurons.
Synonyms: COOL1; KIAA0142; P85SPR; PIXB; Nbla10314; DKFZp761K1021; DKFZp686C12170; BETA-PIX; P85; P85COOL1; P50BP; PAK3; P50; COOL-1
Tractability: PROTAC: ubiquitination databases record sites on it; its protein half-life has been measured.
Gene: Protein-coding gene on chromosome 13 (111,114,559 to 111,305,737, forward strand). Ensembl gene ENSG00000102606.
Subcellular location: Cell junction, focal adhesion; Cell projection, ruffle; Cytoplasm, cell cortex; Cell projection, lamellipodium
Pathways (Reactome):
Signal Transduction: CDC42 GTPase cycle; EGFR downregulation; G alpha (12/13) signalling events; NRAGE signals death through JNK; RAC1 GTPase cycle; RHOA GTPase cycle; RHOJ GTPase cycle; RHOQ GTPase cycle; RHOU GTPase cycle; RHOV GTPase cycle
Developmental Biology: Ephrin signaling
Neuronal System: Activation of RAC1 downstream of NMDARs
Gene Ontology:
Molecular function: gamma-tubulin binding; guanyl-nucleotide exchange factor activity; protein binding; protein kinase binding
Biological process: focal adhesion assembly; Golgi organization; negative regulation of microtubule nucleation; positive regulation of apoptotic process; positive regulation of fibroblast migration; positive regulation of lamellipodium morphogenesis; positive regulation of substrate adhesion-dependent cell spreading; Rho protein signal transduction; ephrin receptor signaling pathway; lamellipodium assembly; signal transduction; intracellular signal transduction
Cellular component: centrosome; focal adhesion; mitotic spindle pole; neuron projection; neuronal cell body; protein-containing complex; cytoplasm; cytosol; lamellipodium; postsynapse; cell cortex; ruffle
Genetic constraint (gnomAD): Loss-of-function variants: 27 observed, 70.26 expected, observed/expected ratio (o/e) 0.38, 90% interval 0.28 to 0.53. The upper end of that interval is the gene's LOEUF score, 0.53, which puts it in group 2 of 6, group 1 being the genes least tolerant of losing a copy. Missense variants: 761 observed, 862.84 expected, observed/expected ratio (o/e) 0.88, 90% interval 0.83 to 0.94. Synonymous variants: 384 observed, 341.26 expected, observed/expected ratio (o/e) 1.13, 90% interval 1.03 to 1.22.
Homologues: Orthologues: chimpanzee ARHGEF7 (99% identical), macaque ARHGEF7 (99% identical), pig ARHGEF7 (95% identical), rat Arhgef7 (95% identical), dog ARHGEF7 (89% identical), tropical clawed frog arhgef7 (89% identical), mouse Arhgef7 (85% identical), guinea pig ARHGEF7 (79% identical), zebrafish arhgef7a (76% identical), zebrafish arhgef7b (69% identical). Paralogues in human: ARHGEF6 (55% identical), MCF2L (18% identical), PLEKHG1 (17% identical), KALRN (17% identical), TRIO (17% identical), PLEKHG4B (16% identical), VAV3 (16% identical), VAV2 (15% identical), VAV1 (15% identical), TIAM1 (15% identical), MCF2 (14% identical), MCF2L2 (14% identical), and 10 more.
Diseases named in the same sentence as ARHGEF7 in open-access papers:
ARHGEF7 is named in the same sentence as 27 diseases in open-access papers, as found by Europe PMC text mining. Sharing a sentence is not in itself a finding about the gene and the disease. The quoted sentences say what the papers report.
colon carcinoma (4 papers, 2012 to 2023). "Arhgef7 CKO mice had 58% fewer colon tumors than control mice (p = 0.03), a stronger effect of βPix deficiency than without MR agonist treatment (p = 0.02, Fisher’s exact test)." (PMID 37805544, 2023). "Arhgef7 CKO mice had 39% fewer colon tumors (3.25 ± 0.47 tumors/control versus 2.00 ± 0.37 tumors/CKO mouse) − 55% fewer adenocarcinomas and 24% fewer adenomas (both p = 0.04)." (PMID 37805544, 2023). "Lastly, we sought an association between ARHGEF7 and PTGS2 expression in colon cancer." (PMID 37805544, 2023). "CHRM3 and ARHGEF7 are in the top 10% overexpressed colon cancer genes." (PMID 37805544, 2023). "We examined the relationship between CHRM3/M3R and ARHGEF7/βPix expression in colon cancer." (PMID 37805544, 2023). "In addition to demonstrating that CHRM3/M3R and ARHGEF7/βPix are coordinately overexpressed in colon cancer, immunoprecipitation experiments revealed that in the cytosol and nucleus M3R activation provokes time-dependent βPix binding to β-catenin by a PKC-dependent mechanism." (PMID 37805544, 2023). "The overexpression of ARHGEF7 in human colon cancer HCT116 and LoVo cells significantly enhanced cell migration and invasion, whereas the knockdown of ARHGEF7 in colorectal adenocarcinoma cells significantly decreased cell migration and invasion." (PMID 32178475, 2020). "Indeed, the lack of a relationship between ARHGEF7 and PTGS2 expression in colon cancer suggests M3R activation is pivotal to augmenting COX2 expression by a βPix-dependent mechanism." (PMID 37805544, 2023).
glioblastoma (4 papers, 2018 to 2026). The most malignant astrocytic tumor (WHO grade IV). "ARHGEF7/βPix/COOL-1 mRNA expression was next assessed within the Ivy Glioblastoma Atlas Project RNAseq dataset (IvyGap GSE107559; N = 41 patients)." (PMID 33256106, 2020).
colorectal adenocarcinoma (3 papers, 2020 to 2022). The most common type of colorectal carcinoma. "Rho guanine nucleotide exchange factor 7 (ARHGEF7) is involved in cytoskeleton remodeling, which is very practical for cell motility and invasiveness, and it demonstrates frequent high-level gene amplification in colorectal adenocarcinoma metastasis." (PMID 33816252, 2021). "Interesting, the ARHGEF7 gene is frequently amplified in metastatic lesions rather than at primary sites in colorectal adenocarcinoma." (PMID 35085554, 2022).
colorectal cancer (3 papers, 2020 to 2023). A primary or metastatic malignant neoplasm that affects the colon or rectum. "Recently whole genome studies of colorectal metastases vs. matched primary tumors extended multistage colorectal cancer progression model with new specific for metastases components ARHGEF7 and ARHGEF33." (PMID 32178475, 2020). "On the other hand, ARHGEF7 prove to be determinants for irinotecan sensitivity of colorectal cancer cell lines." (PMID 32178475, 2020).
breast carcinoma (2 papers, 2017 to 2026). "Breast cancer cell lines showed increased cell migration and invasion upon glutathionylation of ARHGEF7 at C312 in response to both oxidative stress and epidermal growth factor (EGF)." (PMID 42146387, 2026).
metastatic cancer (2 papers, 2024 to 2026). A carcinoma which has spread from the original site of growth to another anatomic site. "In this study, we report on the redox regulation of ARHGEF7, a guanine nucleotide exchange factor highly expressed in metastatic cancer cells, that plays a major role in regulating cell migration." (PMID 42146387, 2026). "ARHGEF7 upregulation is observed in metastatic cancers that increase migration and invasion." (PMID 39303918, 2024).
microcephaly (2 papers, 2025). A congenital or acquired developmental disorder in which the circumference of the head is smaller than normal for the person's age and sex. "We found that STIL, one of the primary microcephaly gene products, is associated with ARHGEF7 in dendritic spines and that knockdown of Stil resulted in a significant reduction in dendritic spines in neurons both in vitro and in vivo." (PMID 39851490, 2025). "Although no direct genetic link with neurological disorders has been identified for βPix, patients with deletions of chromosome bands 13q33-34, including ARHGEF7, exhibit mental retardation and microcephaly, suggesting that ARHGEF7 is a candidate gene." (PMID 39802101, 2025).
Allergy (1 paper, 2025). An allergy is an immune response or reaction to substances that are usually not harmful. "Some of these genes have been previously linked to allergy, such as ARHGEF7, which was found to be differentially expressed in patients with lipid transfer protein (LTP) allergy." (PMID 41394805, 2025).
colon adenocarcinoma (1 paper, 2021). "A cluster of 13 CpG loci (11 genes) were identified that displayed differential methylation in colon adenocarcinoma (COAD) (N = 289) compared to normal colon tissues (N = 38): ZNF671, TWIST1 (two CpG loci), TMEFF2, TM6SF1, GAS7, MAL, HIN1 (two CpG loci; SCGB3A1), COL6A2, AKR1B1, GPX7, ARHGEF7)." (PMID 34903270, 2021).
COVID-19 (1 paper, 2024). A disease caused by infection with severe acute respiratory syndrome coronavirus 2. "Vav guanine nucleotide exchange factor 1(VAV1), the ABR activator of RhoGEF and GTPase (ABR), and the p21-activatedprotein kinase exchange factor beta (ARHGEF7) were GEFs found to beupregulated in mild/severe COVID-19 samples in our study." (PMID 39392878, 2024).
Immunodeficiency (1 paper, 2022). Failure of the immune system to protect the body adequately from infection, due to the absence or insufficiency of some component process or substance. "On the other hand, PAK2 interacting partners such as ARHGEF7, also known as PAK3 (a positive regulator of apoptosis) and Lymphocyte cytosolic protein 2 (LCP2), have been previously linked to human immunodeficiency." (PMID 35783297, 2022).
kidney cancer (1 paper, 2024). Primary or metastatic malignant neoplasm involving the kidney. "Interestingly, CpGs in two genes encoding guannine nucleotide exchanging factors for Rho GTPase (ARHGEF28 and ARHGEF7) were hypomethylated in kidney cancer." (PMID 38336771, 2024).
cancer (11 papers, 2020 to 2026). A tumor composed of atypical neoplastic, often pleomorphic cells that invade other tissues. "More recently, we found that STIL is involved in the regulation of cell motility via direct association with ARHGEF7 in cancer cells." (PMID 39851490, 2025). "Many reports support the critical role of ARHGEF7 in cell spreading and motility associated with wound healing, axon formation, and cancers." (PMID 39303918, 2024). "Since various growth factors, such as EGF, can activate PIP3 production, it is likely that ARHGEF7 more widely contributes to cancer invasion/metastasis caused by amplification and/or mutation of various growth factor receptors." (PMID 35085554, 2022). "Coinciding with this notion, inspection of a publicly available database of large CRISPR-based genetic screens (DEPMAP/PICKLES) unveiled a clear association between sensitivity to loss of PAK2 and loss of its binding partner βPIX (ARHGEF7) across a large panel of pan-cancer cell lines." (PMID 36869386, 2023). "In cancers, it has been shown that ARHGEF7 affects the motility of cancer cells in vitro and invasion in vivo." (PMID 35085554, 2022). "Recently, we reported that ARHGEF7 and PAK1 together associated with STIL, one of the centrosomal proteins, at the lamellipodia protrusion of motile cells and that STIL is involved in the ARHGEF7-mediated activation of cytoskeletal remodeling in cancer cells." (PMID 39851490, 2025). "However, in co-immunoprecipitation (co-IP) experiments using crude neuronal lysates as well as synaptosomal fractions, little binding between endogenous STIL and ARHGEF7 was detected, while we have previously shown binding in cancer cells." (PMID 39851490, 2025). "These lines of evidence underscore the importance of ARHGEF7 in cancer malignancy." (PMID 35085554, 2022). "ARHGEF7 plays a role in cytoskeleton remodeling, and may regulate cancer cell motility, USF1 expression is related to cellular stress and senescence, immune response and carcinogenesis and has been shown to be associated with shorter life expectancy." (PMID 32751422, 2020).
tumor (6 papers, 2009 to 2024). "Its ability to facilitate the interpretation and ubiquitination of the ARHGEF7 protein provides a unique mechanism for inhibiting tumour growth in this context." (PMID 39428564, 2024). "We further showed that ARHGEF7/βPix/COOL-1 expression is increased at the invasive edge in 69% of tumours assessed, when compared with core mRNA expression level." (PMID 33256106, 2020). "For example, the calculation places a recently identified tumor suppressor pathway through ARHGEF7 and Scribble, in the context of growth factor signaling." (PMID 19707567, 2009). "KALRN, MCF2/Dbl, NGEF/EPHEXIN, ARHGEF7/βPix/COOL-1, CDC42EP2, DOCK9, NET1, TIAM2, ABR, PLEKHG5, RhoBTB2 and PREX1 were identified as being increased at the tumour rim." (PMID 33256106, 2020).
adenocarcinoma (1 paper, 2023). A common cancer characterized by the presence of malignant glandular cells. "We compared relative ARHGEF7 and CHRM3 mRNA expression in 17 fresh human adenocarcinomas and paired normal colon." (PMID 37805544, 2023). "Compared to normal colon, median ARHGEF7 and CHRM3 transcript levels were higher in adenocarcinomas [21.734 vs. 18.244 per million for ARHGEF7 (p = 1.3962E-10); 2.528 vs. 1.272 for CHRM3 (p = 0.00236)]." (PMID 37805544, 2023).
ARHGEF7 also shares sentences with these, for which no sentence is quoted: adenoma (2 papers); acute myeloid leukemia (1); cervical cancer (1); hemorrhage (1); Hydrocephalus (1); intracerebral hemorrhage (1); lung carcinoma (1); lung fibrosis (1); melanoma (1); neurological disorders (1); Obesity (1); pancreatic cancer (1).